NFATC3 (nuclear factor of activated T cells 3)
Diseases named in the same sentence as NFATC3 in open-access papers (continued):
Sharing a sentence is not in itself a finding about the gene and the disease.
tumor (46 papers, 2012 to 2026). "In another study, Faecalibaculum and its homology, Holdemanella biformis, demonstrated intestinal antitumorigenic effects through the production of SCFAs, which controlled the protein acetylation and tumor cell proliferation underlying calcineurin inhibition and NFATc3 activation." (PMID 35256637, 2022). "In a study involving retroperitoneal liposarcoma, LINC00423 was reported to act as a tumour-repressing lncRNA by downregulating the MAPK pathway via destabilizing nuclear factor of activated T cells 3 (NFATC3)." (PMID 39736850, 2025). "We also observed diminished expression of Nfatc3 and Il6st, which function as tumor suppressor genes in the mammary gland." (PMID 38334641, 2024). "Firstly, Faecalibaculum rodentium PB1 and Helicia biformis (H. biformis) metabolize butyrate, which inhibits histone deacetylase (HDAC) and activates the NFATc3 transcription factor, leading to the inhibition of tumor cells." (PMID 38617841, 2024). "The resultant increased acetylation leads to downregulation of the calcineurin–NFATc3 pathway, which is involved in tumor cell proliferation." (PMID 38280026, 2024). "Faecalibaculum rodentium, a recently identified antitumor strain, can inhibit the growth of tumor cells and activate calmodulin phosphatase by reducing NFATc3 during the initial stages of tumor development." (PMID 39444688, 2024). "IHC staining results suggested that NFATc3 was mainly expressed in the nucleus in primary PDAC tumor specimens, and in the cytoplasm in the matched normal tissues, respectively." (PMID 35484132, 2022). "Holdemanella biformis and its rodent homolog Faecalibaculum rodentium, as SCFAs-producers, were found to play roles in controlling protein acetylation and tumor cell proliferation by suppressing calcineurin/NFATc3 activation." (PMID 35721506, 2022). "To understand if NFATc3 is a critical factor for cytokines and chemokines known to be involved in tumour growth, we evaluated the impact of nuclear NFATc3 on TNF-α, CXCR-3, GM-CSF, IL-2 and CCL-2 mRNA expression." (PMID 31249342, 2019). "In our study, we, for the first time, demonstrated that NFATC3 can bind with lncRNA, which is regulated by linc00423, and NFATC3 as the tumor suppressor in RLS." (PMID 31160581, 2019). "We have identified NFATc3-dependent genes that are known to be involved in tumour migration: COX-2 and CXCR-3." (PMID 31249342, 2019). "Our data suggest that NFATc1 and especially NFATc3 are overexpressed in tumour samples compared with normal tissue, while NFATc2 is minimally expressed." (PMID 31249342, 2019). "Implanting U251 in an orthotopic intracranial assay, we show that specific NFATc3 silencing has a role in tumour growth." (PMID 31249342, 2019). "Taken together, both linc00423 and NFATC3 were as tumor suppressors in RLS, they make a meaningful contribution to cell proliferation through regulated the MAPK signaling pathway." (PMID 31160581, 2019). "To further examine the effect of NFATc3 on tumor growth in vivo, we injected the cells into nude mice and observed tumor formation." (PMID 31040921, 2019). "We have found that NFATc3 is required for the expression of several mediators known to be involved in tumour growth." (PMID 31249342, 2019). "Summing up, our findings demonstrated that linc00423 acted as the tumor suppressor in RLS cells through regulating the protein level of NFATC3 at a post-transcriptional level and negatively regulated the MAPK signaling pathway at a transcriptional level." (PMID 31160581, 2019). "To investigate an importance of NFATc3 in CSCs, we compared the levels of NFATc3 in tumor spheres and their corresponding adherent monolayer cells derived from multiple OSCC cell lines." (PMID 31040921, 2019). "For the first time we demonstrated NFATC3 can bind with lncRNA, and NFATC3 as the tumor suppressor in RLS." (PMID 31160581, 2019).
tumor (continued). "Increased expression of NFATc3 was required for the maintenance of CSC self-renewal, as NFATc3 inhibition suppressed tumor sphere formation in OSCC cells." (PMID 31040921, 2019). "Ectopic NFATc3 expression resulted in robust induction in tumor sphere formation, indicating the acquisition of self-renewal capacity by NFATc3." (PMID 31040921, 2019). "Significantly higher levels of NFATc3 were detected in GC samples than in corresponding non-tumor tissues (P < 0.01)." (PMID 28881766, 2017). "Knockdown of NFATc3 showed significant suppressive effect on tumor sphere formation and migration in HOK-16B/Orai1 cells." (PMID 27259269, 2016). "Consistent with this, we also demonstrated that silencing of NFATc3 resulted in significant suppression of tumor sphere formation and migration ability in OSCC cells." (PMID 27259269, 2016). "NFATc3 knockdown reduced cell proliferation in vitro and tumor growth in xenograft consistent with its cell growth-promoting effect." (PMID 26795951, 2016). "sFRP2 mAb has been shown to induce anti-tumor and anti-angiogenic effects in vitro and inhibit activation of β-catenin and nuclear factor of activated T-cells c3 (NFATc3) in endothelial and tumor cells." (PMID 26056595, 2014). "The genus Holdemanella has been associated with low cell proliferation of neoplastic cells in humans, due to its production of SCFA—particularly butyrate, which helps control tumour cell proliferation and protein acetylation by inhibition of calcineurin/NFATc3 activation." (PMID 40804998, 2025). "In the nuclei of PDAC cells, NFATc3 could form complexes with other factors to coordinate the expression of target genes to support tumor growth." (PMID 35484132, 2022). "Importantly, our results suggest that anti-SFRP2 therapy not only affects the tumor and endothelial compartments but also the tumor microenvironment through the calcineurin/NFATc3 signaling pathway, leading to a restoration of immunity." (PMID 34070758, 2021). "Analysis of tumor lysates from control(M1, M2) and arsenic sulfide-treated(M3, M4) mice showed an obvious decrease in the expression of NFATc3 proteins, and there was a significant increase in RAG1 and γ-H2AX protein levels in the tumors from mice treated with arsenic sulfide." (PMID 31822296, 2019). "However, NOKSI/NFATc3 cells began to form tumor nodules at 2 week after injection and reached their maximum size by 3 week." (PMID 31040921, 2019). "Knockdown of NFATc3 reduced tumor sphere formation in OSCC cells." (PMID 31040921, 2019). "However, other studies also demonstrated tumor suppressive activity of NFATc2 and NFATc3, suggesting NFAT isoforms play different roles in human cancers in different cellular context." (PMID 31040921, 2019). "Contrastingly, other studies have shown that NFATc2 and NFATc3 can act as tumor suppressors." (PMID 28881766, 2017). "Knockdown of NFATc3 inhibited cell growth in vitro and tumor growth in xenograft." (PMID 26795951, 2016). "Thus, SENP3-mediated NFATc3 deSUMOylation could increase NFATc3 nuclear occupancy and activate NFATc3 signaling for promoting tumor cell proliferation and invasion under hypoxia." (PMID 35484132, 2022). "SENP3-mediated deSUMOylation modulates NFATc3, which is involved in PDAC tumor progression in hypoxic conditions." (PMID 39822413, 2024). "Our results highlight that SENP3-mediated deSUMOylation acts as an essential modulator of NFATc3, which is instrumental in PDAC tumor progression under hypoxia." (PMID 35484132, 2022). "Using tumor samples derived from the tumor xenograft mouse models, we demonstrated that the expression of TRPM7, NFATC3, and ki67 proteins was significantly suppressed in the TRPM7-silenced and combined treatment mice compared with that in the control mice." (PMID 35771152, 2022).
tumor (continued). "To determine the expression pattern and localization of NFATc3 in PDAC, we performed immunohistochemical (IHC) assays in 60 pairs of primary PDAC tumor specimens and their matched normal tissues with the anti-NFATc3 antibody." (PMID 35484132, 2022). "In endothelial and tumor cells, SFRP2 binds to the FZD5 receptor and stimulates the calcineurin/NFATc3 pathway." (PMID 34070758, 2021). "NFATC1, NFATC2, NFATC3, NFATC4, and NFAT5 were all highly expressed in the tumor tissue of the TCGA dataset compared with normal tissue of the GTEx dataset." (PMID 31827081, 2019). "We had previously shown that NFATc3 knockdown impaired colony formation of HCT116 cells and suppressed tumor growth in mice." (PMID 31822296, 2019). "The explanation for our findings was that TRPC1 might promote proliferation via Ca2+ entry and Ca2+- nuclear factor of activated T cells, cytoplasmic 3 (Ca2+-NFATc3) signaling pathways, thus resulting in the RCC growth and subsequently affecting tumor size." (PMID 35548183, 2022). "NFATc3 is highly expressed in CSC-enriched self-renewing OSCC populations, i.e., tumor spheres." (PMID 31040921, 2019). "Consistent with our findings from human cancer, NFATc3 is also the dominant isoform among NFAT isoforms (NFATc1-c4) and significantly increased in the tumor bearing tongue compared to normal tongue, suggesting that increased NFATc3 is associated with chemical-induced oral carcinogenesis." (PMID 31040921, 2019). "Additionally, the 6 markers (KDR, CXCR6, STAT5A, MPL, NFATC3, and TLR6) we found to be downregulated in our late-recurring tumor samples are also biologically relevant to functional T-cell activity, which helps explain their expression and function in this context." (PMID 36195959, 2022). "In addition, we found that the expression levels of T-cell exhaustion-related genes including CD40, GRB2, MKI67, NFATC3, PRDM1, TCF7, and TGFB1 were significantly higher, while those of CXCR5 and TOX were significantly lower after tumor recurrence (all p < 0.05)." (PMID 34305618, 2021). "We first examined messenger RNA (mRNA) expression of NFAT family members (NFATc1, NFATc2, NFATc3, NFATc4, and NFAT5) in 30 pairs of HCC tumor tissues (T) and corresponding adjacent nontumor tissues (NT) by qRT‐PCR." (PMID 30085405, 2018).
cancer (26 papers, 2014 to 2025). A tumor composed of atypical neoplastic, often pleomorphic cells that invade other tissues. "It has been reported that NFAT family including NFATc1, NFATc2, NFATc3, and NFATc4 were closely associated with many kinds of cancers." (PMID 31823518, 2020). "More importantly, the expression of an NFATc3 cDNA carrying synonymous point mutations on the shRNA target sequence rescued the impaired proliferation of cancer cells caused by NFATc3 silencing." (PMID 31822296, 2019). "To investigate whether higher levels of ROS caused by arsenic sulfide treatment alters NFATc3 localization in cancer cells, we treated cells with 1 μM cyclosporine A (CsA, as a positive control) or 5 μM arsenic sulfide for 0, 0.5, 1 and 2 h." (PMID 31822296, 2019). "NFATC3 encodes a member of the nuclear factors of activated T cells DNA-binding transcription complex, and it is important for T-cell development and essential for cancer chemoresistance." (PMID 29633893, 2018). "In ex vivo samples, integration of HIV-1 into NFATC3, a cancer-related gene, was shown to disrupt canonical transcription of the human gene downstream of the HIV-1 integration site." (PMID 35573784, 2022). "We reported that NFATc3 plays an oncogenic role in OSCC by promoting cancer stemness via expression of Oct4." (PMID 36077186, 2022). "The transcriptional regulator nuclear factor of activated T-cells, cytoplasmic 3 (NFATc3) is constitutively activated in several cancer types and plays important roles in cancer development and progression." (PMID 35484132, 2022). "We further noticed that circNFATC3 derived from NFATC3 gene exon 2 and exon 3 was abundant across different cancer cell lines compared to normal cells like HMEC, LL 24, and LCL cells." (PMID 33816459, 2021). "The majority of cancer cell lines showed an abundance of both NFATC3 linear and circular transcripts." (PMID 33816459, 2021). "Many known RBPs are associated with circNFATC3 indicates the regulatory and functional potential circular NFATC3 in cancer and other diseases." (PMID 33816459, 2021). "More importantly, NFATc3 was highly enriched in self-renewing cancer stem-like cells (CSCs) of OSCC." (PMID 31040921, 2019). "PPP3CA is reported to interact with NFATs (NFATc1, NFATc2, NFATc3 and NFATc4) transcriptional factors, and have a crucial role in the regulation of immune response, and invasiveness of cancer cells." (PMID 28881575, 2017). "Recent discoveries, such as NFATc1 pro-angiogenic effect in retinal microvascular endothelial cells, the association of NFATc3 and NFATc4 with immune-related diseases, and the significant contributions of NFAT proteins to cancer progression, highlight the importance of these molecules and pathways." (PMID 39822413, 2024). "NFATC3 gene can inhibit or enhance cancer progression by inducing and modulating other pathways." (PMID 37060021, 2023). "Furthermore, we evaluated TRPM7 and NFATC3 expression in the Gene Expression HNSCC cohort by using the TCGA online open access cancer microarray platform." (PMID 35771152, 2022). "Since chemical inhibitor readily inhibits NFAT signaling, targeting NFATc3 may be a plausible therapeutic modality against cancer." (PMID 31040921, 2019). "Moreover, REDD1 (regulated in development and DNA damage response-1) was known to a target of NFATc3, and its inhibition sensitized human cancer cells to paclitaxel." (PMID 31040921, 2019). "NFATC3 had the significantly lower expression level in various types of cancers." (PMID 31160581, 2019). "Our study indicates that NFATc3 plays an important role in the maintenance of cancer stemness and OSCC progression via novel NFATc3-OCT4 axis, suggesting that this axis may be a potential therapeutic target for OSCC CSCs." (PMID 31040921, 2019). "Our observations so far support the hypothesis that NFATc3 promotes cancer stemness by upregulating CSC factors, including OCT4." (PMID 31040921, 2019).
cancer (continued). "Moreover, ectopic expression of NFATc3 resulted in the acquisition of malignant growth phenotype in the non-tumorigenic immortalized oral epithelial cells, indicating the function of NFATc3 in cell transformation and cancer progression." (PMID 31040921, 2019). "Furthermore, by using constitutive active NFATc3 mutant and shRNA lentiviral vectors to achieve specific silencing of this NFATc member, we describe cytokines and molecules regulated by this pathway which are required for the normal biology of cancer cells." (PMID 31249342, 2019). "Mechanistically, nuclear factor of activated T cells 3 (NFATc3) promoted CPT2 expression transcriptionally, and inhibiting CPT2 resensitized cancer cells to oxaliplatin." (PMID 35646898, 2022). "Additionally, the NFATc3/SRPX2 axis participates in human embryonic stem cell differentiation, indicating that SRPX2 plays a critical role in pan-cancers." (PMID 34660598, 2021).
cardiac diseases (4 papers, 2014 to 2016). "Recent experimentally validated targets for miR-185, such as Camk2d, Ncx1, and Nfatc3 have been related to cardiac diseases." (PMID 27137793, 2016). "Previous studies uncovered that the activation of calcineurin/NFATc3 signalling pathway might contribute to potassium channel pattern in heart diseases." (PMID 24780005, 2014).
infection (4 papers, 2016 to 2021). The state of being infected such as from the introduction of a foreign agent such as serum, vaccine, antigenic substance or organism. "Supporting these data, we found Nfatc3, a transcription factor shown to activate GM-CSF transcription and other cytokines, to be upregulated in response to secondary infection." (PMID 34975887, 2021). "In this model, we also found that some genes exhibited a downward trend (e.g., Ptgs2, Rel, IL4r, CXCL1, CXCL2, TLR5, Nfatc3 and Egr2) in M. fortis after infection." (PMID 28900150, 2017).
inflammation (2 papers, 2020 to 2023). Aberrant reaction of the microcirculation characterized by movement of fluid and leukocytes from the blood into extravascular tissues. "Therefore, mice deficient in NFATc3 are protected from BLM-induced lung inflammation and fibrosis." (PMID 37523510, 2023).
bacterial infection (1 paper, 2018). "Interestingly, NFATc3−/− mice showed increased bacterial infection in CLP mouse lungs due to decreased iNOS expression by macrophages, but significantly improved survival compared to WT mice when subjected to lethal CLP in presence of antibiotics." (PMID 29535830, 2018).
cardiovascular disease (1 paper, 2023). "NFAT protein family is the main substrate of CaN and includes NFAT1 (NFATc2), NFAT2 (NFATc1), NFAT3 (NFATc4), NFAT4 (NFATc3) and NFAT5, among which NFATc3 protein is highly related to the development of cardiovascular disease." (PMID 37735624, 2023).
kidney diseases (1 paper, 2025). "Not only does this research contribute to unveiling the molecular mechanisms of podocyte damage in MN, but it also provides new insights into the synergistic effects of NFATc3/LRRC55/BK channels in the pathophysiology of renal diseases." (PMID 40520074, 2025). "Although previous research has explored the role of ion channels in kidney diseases, our study is the first to establish a direct link between NFATc3 and ion channels in this context." (PMID 40520074, 2025). "Furthermore, targeted interventions against the NFATc3/LRRC55/BK channel axis may represent novel therapeutic approaches for MN and other related renal diseases, enhancing the quality of life for patients with renal diseases and slowing the progression of renal failure." (PMID 40520074, 2025).
NFATC3 also shares sentences with these, for which no sentence is quoted: Alzheimer disease (3 papers); hypertrophy (3); amyloid (2); brain injury (2); heart failure (2); idiopathic pulmonary fibrosis (2); Insulin resistance (2); leukemia (2); nasopharyngeal carcinoma (2); ulcerative colitis (2); abdominal aortic aneurysm (1); acute monocyte leukemia (1); acute respiratory distress syndrome (1); angiosarcoma (1); asthma (1); breast tumours (1); chronic kidney disease (1); dementia (1); depression (1); edema (1); Hepatitis B (1); HIV-1 infection (1); Hypercalcemia (1); lung carcinoid tumor (1); Lymphadenopathy (1); lymphoproliferative disorder (1); mammary adenocarcinoma (1); melanoma (1); membranous nephropathy (1); multiple myeloma (1).
A further 11 diseases each share a sentence with NFATC3 in 1 paper.